SCYGR2 (small cysteine and glycine repeat containing 2)
Description:
In the hair cortex, hair keratin intermediate filaments are embedded in an interfilamentous matrix, consisting of hair keratin-associated proteins (KRTAP), which are essential for the formation of a rigid and resistant hair shaft through their extensive disulfide bond cross-linking with abundant cysteine residues of hair keratins. The matrix proteins include the high-sulfur and high-glycine-tyrosine keratins.
Synonyms: KRTAP28-2
Gene: Protein-coding gene on chromosome 2 (227,598,893 to 227,599,255, forward strand). Ensembl gene ENSG00000284643.
Homologues: Orthologues: dog SCYGR2 (77% identical).